IL1B (interleukin 1 beta)
Diseases named in the same sentence as IL1B in open-access papers (continued):
Sharing a sentence is not in itself a finding about the gene and the disease.
ischemia (continued). "In the present study, we observed transient increases in pro-inflammatory cytokines, such as IL-1β, IL-6, and TNF-α in the spinal cord after ischemia, indicating inflammation." (PMID 33050051, 2020). "At day 7, global ischemia-induced NLRP3 inflammasome activation, as evidenced by an increase in the expression of NLRP3, and IL-1β in the hippocampus compared to Sham controls." (PMID 32466385, 2020). "Elsewhere, administration of BBG decreased superoxide dismutase (SOD), malondialdehyde (MDA), TNF-α, and IL-1β concentration in pulmonary arterial hypertension (PAH) and ischemia-reperfusion- (IR-) induced lung models." (PMID 32566102, 2020). "HLJDT was proven to reduce the production of proinflammatory factors including IL-1β, TNF-α, IL-6, as well as IL-17, thus it is of great significance in alleviating ischemia." (PMID 33613277, 2020). "The IL-1β in the Tat peptide- and Control-PGAM1-treated groups transiently increased at 24 h after ischemia and decreased 72 h after ischemia, when compared to the basal level." (PMID 33050051, 2020). "RT-qPCR showed that the expression levels of proinflammatory cytokines (IFN-γ, TNF-α, IL-1β) and the chemokine (MCP-1) mRNAs were significantly increased at 4 and 24 h after ischemia, and their increases were profoundly inhibited by CD147 inhibition." (PMID 31666088, 2019). "Our results indicate that rTMS reduces inflammation-related gene expression (IL1β, TNFα, MMP9, and TGFβ), as suggested using a pulsed electromagnetic field following ischemia." (PMID 31031599, 2019). "Our data demonstrated that the concentrations of IL-1β (6, 24, and 72 h after reperfusion) and TNF-α (6 and 24 h after reperfusion) in serum were significantly enhanced after ischemia." (PMID 29540536, 2018). "Microglia secrete pro-inflammatory cytokines, like IL-1β and TNF-α, after being stimulated by ischemia or infection." (PMID 29665808, 2018). "At post-translational levels, IL-1β and cyclooxygenase-2 (COX-2) expressions were significantly higher following hyperglycemic ischemia than hyperglycemic shams." (PMID 28115020, 2017). "In our real-time PCR experiments, though, we already observed robust increases of both IL-1β and TNF-α expression at 4 h of permanent MCAO induced ischemia." (PMID 27544687, 2016). "According to some reports, IL-1β and TNF-α expression begin to increase between 4 and 6 h after the onset of ischemia." (PMID 27544687, 2016). "We detected the expression of mRNAs for various inflammatory cytokines (IL-1β, TNF-α, IL-6, IL-10, and TGF-β) in the cortex ipsilateral to sites of ischemia 24, 48, and 72 h after reperfusion." (PMID 27549161, 2016). "In the ischemia + PPG group, the TNF-α, IL-1β and IL-6 levels in the serum were significantly increased, the expression of ICAM-1 mRNA was increased, although without a significant difference, and the expression of NF-κB was increased." (PMID 25667680, 2015). "The protective mechanism of ischemic postconditioning was investigated by comparing its effects on apoptosis, production of the neurotoxic cytokine IL-1β and the transcription and expression of TLR2, TLR4 and IRAK4 in the 2 and 4.5 hour ischemia groups." (PMID 24460643, 2014). "Moreover, endogenous IL-18 is induced by IL-1β via caspase-1 under ischemic conditions in human myocardial tissue and that inhibition of caspase-1 reduces the processing of endogenous precursors of IL-18 and IL-1β and thereby prevents ischemia-induced myocardial dysfunction." (PMID 24115947, 2013). "During ischemia, cytokines, such as TNF-α, IL-1β, IL-6, and chemokines such as cytokine-induced neutrophil chemoattractant (CINC) and MCP-1 are produced by a variety of activated cell types, including endothelial cells, microglia, astrocytes and neurons." (PMID 23663236, 2013). "Similar to VEGF and FGF-2, IL-1β, MCP-1, and SDF-1 are known as proangiogenic factors induced by ischemia." (PMID 22529991, 2012).
ischemia (continued). "It is demonstrated that hypoxia-inducible factor-1α (HIF-1α), interleukin-1 β (IL-1β) and tumor necrosis factor α (TNF-α) expression increase in the rat brain during cerebral ischemia induced by different models of ischemia." (PMID 23351182, 2012). "Further supporting the effect of lithium on neuroinflammation is the recent finding that lithium reduced microglial activation and inhibited the production of classical inflammatory cytokines IL-1β and MCP-1 in a rat model of hypoxia-ischemia." (PMID 22347510, 2012). "During ischemia, cytokines, such as TNF-α, IL-1β, IL-6, and chemokines such as CINC and MCP-1 are produced by a variety of activated cell types, including endothelial cells, microglia, astrocytes and neurons." (PMID 22196138, 2011). "In the two ischemia groups our measurements indicated an mRNA up-regulation of TNF-α, IL-1β, and IL-6 that was unaffected by COX-2 enzyme blockage." (PMID 17150094, 2006). "Additionally, the E-MSC-treated ischemia groups showed a substantial reduction in inflammatory cytokine (TNF-α, IL-1β, IL-6, and TGF-β) levels and a notable increase in angiogenetic cytokine (ANG1, FGF, VEGF, and PDGF) levels compared to the control group." (PMID 40595285, 2025). "The expression levels of inflammatory factors IL‐1β, TNF‐α, and IL‐6 were simultaneously increased in both the ipsilateral L Core and L Edge at 3 days post‐ischemia, whereas the levels of these factors in the L Cortex region were similar to the contralateral side." (PMID 39252446, 2024). "In addition, intravenous administration of hUC-MSCs effectively downregulated the expression of pro-inflammatory cytokines, including IL-1β, TNF-α, matrix metalloproteinase 9, and IL-6, which are upregulated by ischemia." (PMID 36829224, 2023). "Other studies have found that neutrophils can produce pro-inflammatory factors (such as IL-1β) and release a variety of proteases (including ROS and MMP-9) in the acute phase after ischemia, leading to the destruction of the BBB and further aggravating post-ischemic inflammatory damage." (PMID 37253636, 2023). "Pro-inflammatory cytokines, such as IL-1β, IL-6, and TNF-α, were significantly increased in the hippocampus after ischemia induction, and Tat-CHIP attenuated the increase in pro-inflammatory cytokine release, suggesting the anti-inflammatory potential of Tat-CHIP in ischemic damage." (PMID 36450819, 2022). "In the purpurin-treated ischemic group, IL-1β, IL-6, and TNF-α levels were significantly lower than those in vehicle-treated ischemic group and were 203.2%, 178.2%, and 626.1% of those in the control group 6 h after ischemia, respectively." (PMID 35094304, 2022). "Moreover, the pro-inflammatory factors COX-2, IL-6, IL-1β, and TNF-α were rarely expressed in the sham group, while their expression was remarkably elevated after ischemia." (PMID 35082676, 2021). "Moreover, magnesium isoglycyrrhizinate suppressed the levels of TNF-α, IL-1β, IL-6, antioxidant enzymes (SOD, GSHPx), iNOS, and caspase-3 in ischemia-reperfusion injury model rats." (PMID 34220502, 2021). "In addition, we observed the significant reduction of pro-inflammatory cytokines such as IL-6, IL-1β, and TNF-α in hippocampal homogenates 6 h after ischemia." (PMID 33435613, 2021). "We observed the levels of IL-6, IL-1β, and TNF-α in the hippocampus 6 h after ischemia because these pro-inflammatory cytokines are increased biphasically, with a prominent increase at this early period after ischemia." (PMID 33435613, 2021). "In a previous report after generalized ischemia, we indeed also observed that IL-6 was activated very early, whereas IL-1β or tumor necrosis factor-alpha were not." (PMID 33806919, 2021). "The rhSLPI treatment at reperfusion was able to drastically decrease the IL-1β level while rhSLPI treatment during ischemia was not." (PMID 33924676, 2021).
ischemia (continued). "When ischemia occurs, the expression of mmu-miR-155 was significantly upregulated, and inhibiting mmu-miR-155 could reduce the secretion of TNF-α, IL6, IL1β, and IFN-γ induced by neuroinflammation." (PMID 34457020, 2021). "Serum samples were collected and heart-type fatty acid binding protein (H-FABP), ischemia modified albumin (IMA), interleukin-1β (IL-1β), and interleukin-18 (IL-18) were measured to observe whether Sevoflurane anesthesia had protective effect on myocardium." (PMID 34765646, 2021). "In the present study, we analyzed the levels of TNF-α, IL-1β, and IL-6 in the hippocampus to validate the roles of Tat-SH3GL2 on ischemia-induced inflammatory responses because TNF-α promotes the migration of neurotrophils, IL-1β, and IL-6, which show pro-inflammatory roles." (PMID 33572372, 2021). "Moreover, treatment with 100 mg/Kg bacailin significantly reduces the levels of pro-inflammatory cytokines, including IL-1β, IL-6, and TNF-α in the hippocampus of ischemia mice." (PMID 32084011, 2020). "Additionally, it inhibited the expression of NF-κB p65, IL-1β, and TNF-α and reduced the conversion of microglia to the M1 phenotype after ischemia." (PMID 32922507, 2020). "Those with the M1 polarized phenotype secrete pro-inflammatory cytokines, such as IL-6, IL-1β, and TNF-α, which may further aggravate neuroinflammation in the peri-infarct region after ischemia and reperfusion injury." (PMID 31640144, 2019). "In accordance with the previous reports, our results showed increased inflammatory responses in a model of concurrent global ischemia superimposed on a model of aging in mice, while both PBM and/or CoQ10 partially, but significantly, attenuated the expression levels of TNF-α and IL-1β." (PMID 30983970, 2019). "In the first 3–12 h after myocardial ischemia, expression of IL-1β and IL-6 was significantly increased in both ischemia and non-ischemic myocardium." (PMID 31287006, 2019). "The splenic inflammatory response induced by cerebral ischemia was inhibited by αCD147 treatment as demonstrated by the reduced expression of cytokines (TNFα, IL-6, IL-1β) and monocyte chemoattractant protein-1 (MCP-1) in the spleen at 4 and 24 h after ischemia onset." (PMID 31666088, 2019). "The ischemia-related increases in apoptosis were predominately diminished in non-neuronal cells after treatment with anti-IL-1β mAb, suggesting that the mAb exerted its effects mainly on glial cells." (PMID 29875342, 2018). "Increased levels of IL-1β and TNF-α after ischemia are correlated with infarct severity." (PMID 28592261, 2017). "Indeed, EP4 agonist significantly attenuated the production of TNFα, IL-6, IL-1β, and MCP-1 as well as macrophage infiltration in the heart after ischemia." (PMID 27190998, 2016). "As plasma levels of IL1-β and TNF-α as apoptotic factors and inflammatory mediators were significantly elevated in I/R group compared to the control group, however, they were significantly decreased in ischemia only group compared to I/R group." (PMID 28101298, 2016). "Compared to the sham-operated group, both TNF-α and IL-1β were markedly higher after ischemic injury in the ischemia group (P<0.05); however, treatment with LXW7 suppressed the expression of TNF-α and IL-1β, by 29 and 39%, respectively, compared to the ischemia group (P<0.05)." (PMID 27533766, 2016). "Injection of IL-1β into specific brain regions has been found to exacerbate neuronal damage, regardless of the primary insult (e.g., trauma, ischemia)." (PMID 25592846, 2015). "Mild positivity of immunoreaction (tryptase, CD15, IL-1β, IL-6, IL-8, TNF-α) and stronger reactivity for IL-15, MCP-1 in areas where depletion of cellular antigens (myoglobin and cardiac troponin) is detectable within 30 – 40 minutes from ischemia." (PMID 24989171, 2014).
ischemia (continued). "In cultured microglia, activation by several stimuli depends on NHE1 mediated H+ homeostasis and inhibition of NHE1 with HOE 642 also reduced the production of superoxide anions as well as proinflammatory cytokines IL-1β, IL-6, and TNF-α induced by LPS or in vitro ischemia." (PMID 24392123, 2014). "Our study showed that ischemic postconditioning inhibited the production IL-1β in the 2 hour ischemia group, not in 4.5 hour ischemia group, which might be the reason underlying the differential protection of ischemic postconditioning between the 2 hour ischemia group and 4.5 hour ischemia group." (PMID 24460643, 2014). "In the initial stages of ischemia, neural and glial cells in the brain are activated by the lack of blood flow and oxygen, leading to the release of inflammatory mediators such as tumor necrosis factor-alpha (TNF-α), interleukin-1 beta (IL-1β), and interleukin-6 (IL-6)." (PMID 40421420, 2025). "Interestingly, we observed that Tat-NTS peptide modulated ischemic brain injury-induced microglial polarization towards the anti-inflammatory phenotype and robustly decreased the expression of pro-inflammatory mediators IL-1β and TNF-α in ischemia-stimulated microglia." (PMID 37908731, 2023). "Similarly, EPO also reduced post-ischemic upregulated mRNA levels of IL-1β at both reperfusion timepoints, while the other cleavage product of inflammasomes, IL-18, did not appear to be affected by either ischemia or EPO administration." (PMID 34628598, 2022). "In addition, the expression levels of IL-1β and cyclooxygenase-2 (COX-2) were also elevated 3 h after MCAO, and administration of CH223191 clearly suppressed the increment, showing that AhR-mediated inflammation occurs during ischemia." (PMID 33804845, 2021). "In addition, Tat-PGAM1, but not Control-PGAM1, significantly decreased microglial activation and secretion of pro-inflammatory cytokines, such as interleukin (IL)-1β, IL-6, and tumor necrosis factor (TNF)-α induced by ischemia in the ventral horn of the spinal cord." (PMID 33050051, 2020). "We found that serum inflammatory cytokines, including IL-6, IL-1β, and TNF-α, were significantly decreased by MLB during hepatic ischemia/reperfusion (I/R) injury, suggesting that MLB may alleviate hepatic I/R injury via inhibiting inflammatory signaling pathways." (PMID 31231218, 2019). "The confocal images showed that the expression of TNF-α and IL-1β in the activated microglia was significantly higher 24 h after the ischemic injury, compared to the sham-operated group, but it was markedly lower after treatment with LXW7 (compared to the ischemia group)." (PMID 27533766, 2016). "Our hypothesis is further supported by the evidence that either chemical and ischemic preconditioning was shown to attenuate ischemia-induced mRNA elevations of inflammatory cytokines (i.e., IL-1β and IL-6), while not affecting the elevation of the protective TGF-β occurring in the ischemic cortex." (PMID 35359933, 2022). "Comparing these findings, we found inhibitor of P38 MAPK decreased effectively the level of IL-1β expression and significantly improved the lung injury, which may be important to give a new cure by administration of P38 MAPK to interfere ALI after intestinal ischemia reperfusion." (PMID 26980948, 2016). "During ischemia, inflammatory cells like macrophages may migrate into the ischemic myocardium and produce proinflammatory cytokines and chemokines, including TNFα, interleukin 6 (IL6), IL-1β, and monocyte chemotactic protein 1 (MCP-1), which further exacerbate myocardial I/R injury." (PMID 27190998, 2016). "In the HFD/RAPA 2-min TI group, IL-1β and TNF-α levels were significantly decreased (about 1.7-fold, p < 0.001, and 1.8-fold, p < 0.001 of the HFD 2-min TI group, respectively) at 2 days post-ischemia, and the decreased levels were not altered until 5 days post-ischemia." (PMID 31546722, 2019).
ischemic stroke (251 papers, 2008 to 2026). A stroke disorder caused by obstruction of blood flow to the brain, due to thrombotic (local blood clot formation) or embolic (due to a blood clot or other material traveling from another site) event. "The study aims to evaluate the link among the IL-1β (rs16944) and IL-10 (rs1800896) polymorphisms and ischemic stroke in Egyptians, in addition to the role of additional risk variables." (PMID 40369205, 2025). "A study conducted in an experimental ischemic stroke model found that neuronal, vascular and oligodendrocyte damage caused by IL-1β overexpression in the central nervous system (CNS) was significantly increased." (PMID 39766497, 2024). "IL1B gene polymorphisms affect the risk of MI and ischemic stroke in young adults by modulating the expression of NF‐κB, iNOS, MMP‐2, and Bax." (PMID 38526027, 2024). "It was found that NLRP1, ASITN/SIR grade, infarct volume, NIHSS, IL-6, and IL-1β were the risk factors for bad prognosis of ischemic stroke patients." (PMID 37000063, 2023). "Clinical studies show that higher plasma levels of IL-1β are associated with worst impairment in patients with ischemic stroke." (PMID 36745280, 2023). "Strokes caused by an ischemic stroke can induce the release of inflammatory cytokines, including IL-1β and IL-18." (PMID 36105479, 2022). "The NLRP3 inflammasome regulates the release of pro-inflammatory factors IL-1β and IL-18, one of the critical steps leading to neuronal cell death associated with ischemic stroke." (PMID 36232980, 2022). "For instance, SC downregulated the levels of proinflammatory factors (TNF-α, IL-1β, and IL-6), while upregulated the activities of antioxidant enzymes in cardiomyocyte hypoxia; a complication usually occurs associated with ischemic stroke." (PMID 32240450, 2020). "Single nucleotide polymorphisms have been found in several genes related to inflammation and ischemic stroke; these polymorphisms include the following: IL-1β, IL-6, IL-10, MMP-2, MMP-9, MMP-12, E-selectin, L-selectin, CD36, PCSK9, and adiponectin." (PMID 33153204, 2020). "It is known that macrophage chemoattract proteins produced after ischemic stroke stimulated IL-1β release and activated nitric oxide synthase which caused the further progression of tissue damage." (PMID 31722731, 2019). "Classically, three pro-inflammatory cytokines, IL-1β, IL-6, and TNFα are associated with the inflammatory response following ischemic stroke." (PMID 29426336, 2018). "TNF-α and IL-1β are risk factors for ischemic stroke in humans and result in neurotoxicity in rats after an ischemic event." (PMID 30237808, 2018). "Two frequent proinflammatory cytokine variants in the IL-10 and IL-1β genes, rs16944 T/C and rs1800896 G/A, may be major candidate gene loci impacting ischemic stroke vulnerability." (PMID 40369205, 2025). "In addition, higher plasma IL-1β levels are associated with the most severe damage in patients with ischemic stroke." (PMID 39139639, 2024). "Furthermore, a randomized controlled study of ischemic stroke patients demonstrated that tumor necrosis factor-α and the interleukins (IL), such as IL-1β, IL-6, and IL-20, were associated with inflammation in ischemic stroke." (PMID 37533068, 2023). "The upregulation of IL-20 on glial pro-inflammatory cytokines and chemokines (may cooperate with IL-1β to promote inflammatory activity) is associated with inflammatory response and brain damage after ischemic stroke." (PMID 35173738, 2022). "However, in our study, the association between IL-1b and ischemic stroke was attenuated (OR:1.08, 95%CI: 0.99–1.16, p = 0.07)." (PMID 35111052, 2021). "In a study, IL-1β levels were correlated with a poor prognosis and reduced long-term functional recovery, on the other hand, IL-1Ra levels seemed to be related to a higher risk of infections after the ischemic stroke." (PMID 32899616, 2020).